MOCS1 (molybdenum cofactor synthesis 1)
Description:
Isoform MOCS1A and isoform MOCS1B probably form a complex that catalyzes the conversion of 5'-GTP to cyclic pyranopterin monophosphate (cPMP). MOCS1A catalyzes the cyclization of GTP to (8S)-3',8-cyclo-7,8-dihydroguanosine 5'-triphosphate and MOCS1B catalyzes the subsequent conversion of (8S)-3',8-cyclo-7,8-dihydroguanosine 5'-triphosphate to cPMP. [Isoform 9]: Has very weak catalytic activity.
Synonyms: MIG11; MOCOD; MOCS1A; MOCS1B
Tractability: No criterion of Open Targets' tractability assessment is met for any kind of drug.
Gene: Protein-coding gene on chromosome 6 (39,899,578 to 39,934,551, reverse strand). Ensembl gene ENSG00000124615.
Subcellular location: Mitochondrion matrix (Isoform MOCS1A); Mitochondrion matrix (Isoform MOCS1B); Mitochondrion matrix (Isoform 9); Cytoplasm, cytosol (Isoform 2); Cytoplasm (Isoform 3); Mitochondrion matrix (Isoform 8)
Subcellular location (Human Protein Atlas): Cytosol
Pathways (Reactome):
Metabolism: Molybdenum cofactor biosynthesis
Gene Ontology:
Molecular function: cyclic pyranopterin monophosphate synthase activity; GTP 3',8'-cyclase activity; 4 iron, 4 sulfur cluster binding; catalytic activity; iron-sulfur cluster binding; metal ion binding; S-adenosyl-L-methionine binding
Biological process: Mo-molybdopterin cofactor biosynthetic process; molybdopterin cofactor biosynthetic process
Cellular component: cytoplasm; cytosol; mitochondrial matrix; mitochondrion
Genetic constraint (gnomAD): Loss-of-function variants: 40 observed, 58.71 expected, observed/expected ratio (o/e) 0.68, 90% interval 0.53 to 0.89. The upper end of that interval is the gene's LOEUF score, 0.89, which puts it in group 3 of 6, group 1 being the genes least tolerant of losing a copy. Missense variants: 795 observed, 846.62 expected, observed/expected ratio (o/e) 0.94, 90% interval 0.88 to 1. Synonymous variants: 334 observed, 338.05 expected, observed/expected ratio (o/e) 0.99, 90% interval 0.9 to 1.08.
Gene-disease validity (ClinGen):
ClinGen rates the evidence that MOCS1 causes each of these diseases.
sulfite oxidase deficiency due to molybdenum cofactor deficiency type A (autosomal recessive): Definitive.
Homologues: Orthologues: chimpanzee MOCS1 (99% identical), macaque MOCS1 (94% identical), pig MOCS1 (87% identical), mouse Mocs1 (85% identical), guinea pig MOCS1 (84% identical), rat Mocs1 (84% identical), rabbit MOCS1 (77% identical), dog MOCS1 (76% identical), tropical clawed frog mocs1 (65% identical), Drosophila melanogaster Mocs1 (47% identical), zebrafish mocs1 (42% identical), Caenorhabditis elegans moc-5 (40% identical), and 1 more.
Diseases named in the same sentence as MOCS1 in open-access papers:
MOCS1 is named in the same sentence as 14 diseases in open-access papers, as found by Europe PMC text mining. Sharing a sentence is not in itself a finding about the gene and the disease. The quoted sentences say what the papers report.
molybdenum cofactor deficiency (6 papers, 2011 to 2025). "Xanthinuria type III is caused by molybdenum cofactor deficiency (MoCD) due to pathogenic variants in MOCS1, MOCS2, MOCS3, or GEPH genes." (PMID 40707723, 2025). "Molybdenum cofactor deficiency (MoCD) is a rare and severe autosomal recessive in-born error of metabolism caused by the mutation in MOCS1, MOCS2, MOCS3 or GEPH genes, with an incidence ranging between 1 in 100,000 and 200,000 live births." (PMID 37371303, 2023). "MOCS1 was essential for synthesis of molybdenum cofactor, and gene mutation of MOCS1 was associated with molybdenum cofactor deficiency." (PMID 37120564, 2023). "Mutations in MOCS1 causes molybdenum cofactor deficiency which is characterized by neurodegeneration and seizures." (PMID 32493431, 2020). "Known mutations within MOCS1 lead to an autosomal recessive disease, the molybdenum cofactor deficiency, with neurological symptoms in humans." (PMID 21255426, 2011). "Additionally, a mutation in MOCS1, associated with molybdenum cofactor deficiency of complementation group A, was found." (PMID 40336053, 2025).
lung carcinoma (1 paper, 2023). "Our study identified the prognostic role of MOCS1 in lung cancer for the first time." (PMID 37120564, 2023).
molybdenum cofactor deficiency type A (1 paper, 2026). "We report the case of an 18-year-old male with genetically confirmed molybdenum cofactor deficiency type A (MoCD-A) due to a homozygous pathogenic MOCS1 variant." (PMID 41658802, 2026).
Obesity (1 paper, 2025). Accumulation of substantial excess body fat. "MOCS1 expression has not been associated with obesity or MetS so far." (PMID 40229590, 2025). "The genes glycerol‐3‐phosphate dehydrogenase 1 like (GPD1L), gasdermin B (GSDMB) and molybdenum cofactor synthesis 1 (MOCS1) were upregulated after LIWL, and expression was increased in SAT of individuals with or without obesity of the LATC and OA cohorts." (PMID 40229590, 2025).
xanthinuria (1 paper, 2024). A metabolic metabolic disorder characterized by excess urinary excretion of the purine base xanthine. "Genetic causes of xanthinuria with NL and/or NC consist of Xanthinuria (XDH and MOCOS genes) and Molybdenum cofactor deficiency (MOCS1 and MOCS2 genes)." (PMID 38606357, 2024).
cancer (3 papers, 2022 to 2023). A tumor composed of atypical neoplastic, often pleomorphic cells that invade other tissues. "The R_cancer prognosis features and risk score were calculated as: MOCS1 × 1.100 − PTGS2 × 0.722 + PLEKHA8P1 × 0.409 − ZC3H12C × 0.571 + LPO × 0.575 + METTL11B × 0.294 + RP11-278A23.1 × 0.508 + RP11-452K12.7 × 0.405 − RP11-742B18.1 × 0.360 + RP11-626H12.2 × 0.787." (PMID 36419007, 2022). "MOCS1 was negatively correlated with immune-related pathways, and we found global dysfunction of cancer-related pathways among the three MOCS subtypes." (PMID 37091151, 2023). "MOCS1 is a gene involved in the molybdenum cofactor biosynthesis pathway but little was known about its function in malignancies." (PMID 36816023, 2023).
MOCS1 also shares sentences with these, for which no sentence is quoted: behavioral disorders (1 paper); biotinidase deficiency (1); Encephalopathy (1); hereditary xanthinuria (1); microcephaly (1); nonketotic hyperglycinemia (1); pancreatic cancer (1); Stillbirth (1).